FOXM1 (forkhead box M1)
Diseases named in the same sentence as FOXM1 in open-access papers (continued):
Sharing a sentence is not in itself a finding about the gene and the disease.
glioma (continued). "Therefore, exploring the potential mechanism by which FoxM1 acts on UBE2C may provide a novel therapeutic approach for treating gliomas." (PMID 28767320, 2017). "MYBL2 is a key downstream factor of Akt/FoxM1 signaling to promote progression of human glioma, and could be a new candidate gene for molecular targeting therapy and biomarker for radiotherapy of glioma." (PMID 28784180, 2017). "Consistent with NS-culture-derived glioma cells with high invasiveness, genes highly expressed in 51A were those encoding markers of neural stem/precursor cells (NANOG, POU3F2, POU5F1, and SALL2), and pro-invasive proteins (AGAP2, EPHA2, FOXM1, PDGFRA, and TNC)." (PMID 29113349, 2017). "Further studies showed that PHGDH interacts with N-terminal of FOXM1, stabilized FOXM1 from ubiqutintion induced protesome degradation in glioma cells, suggesting that PHGDH may be a regulator of FOXM1, and that PHGDH has additional biological functions in addition to those as a metabolic enzyme." (PMID 23229761, 2013). "Therefore, our results suggest that Anxa1 expression related to FoxM1 expression in human glioma tissues and the Anxa1/FoxM1 expression might be useful to predict the outcome in patients with glioblatoma." (PMID 23991102, 2013). "To observe the relationship between FoxM1 and TFAM, we first analyzed the expression levels of FoxM1 and TFAM in glioma specimens from TCGA." (PMID 41323781, 2025). "The observation with the mutants further implying a positive regulatory relationship between FoxM1 and TFAM in glioma cells." (PMID 41323781, 2025). "In glioma cells, ALKBH5 demethylates FOXM1 mRNA at m6A sites within the 3′-UTR regions, facilitating the binding of the RNA-binding protein HuR to FOXM1 pre-mRNA in the nucleus, ultimately enhancing FOXM1 expression." (PMID 40186131, 2025). "In conclusion, our experimental evidence underscores the critical role of FoxM1 N-terminal domain R15 in its transcriptional activity, nuclear localization, TFAM expression and regulation of mitochondrial dynamics in glioma cells." (PMID 41323781, 2025). "In gliomas, PHGDH interacts with the oncogenic transcription factor FOXM1 to promote glioma cell proliferation and invasion." (PMID 41415540, 2025). "On the other hand, the combination of TMZ with a FOXM1 inhibitor, thiostrepton, has been shown to enhance TMZ-induced apoptosis in glioma cells." (PMID 39594778, 2024). "Inhibition of FOXM1 or RFC5 sensitizes glioma cells to Temozolomide (TMZ), a first-line standard therapeutic drug, indicating that FOXM1 induces TMZ resistance." (PMID 39594778, 2024). "Similar to FOXM1, various studies have identified upstream/downstream regulators of FOXO1 in gliomas." (PMID 37821870, 2023). "Some studies have elucidated the anti-FOXM1 activity of MELK and proteasome inhibitors as well as natural products on glioma." (PMID 37821870, 2023). "A previous study has shown that ASPM was highly expressed in glioma cells, and the abnormal expression of ASPM regulated by transcriptional regulation of FoxM1 contributed to the aggressiveness of gliomas." (PMID 37229243, 2023). "Several studies have found that FOXM1 level is upregulated in GSCs by ALKBH5, SATB2 and other molecular to keep glioma stemness." (PMID 37620304, 2023). "An example is forkhead box M1 (FOX1) and its target survivin, which are upregulated in gliomas, and their high expression correlates with poor patient prognosis." (PMID 37626776, 2023). "In this study, we analysed the FOXM1 gene in the UCSC database, screened circFOXM1 (circ_0025033) to further explore its role in glioma." (PMID 35013157, 2022). "Down regulation of FoxM1 and MYBL2 by siRNAs induced the cell cycle blocking, apoptosis and EMT (Epithelial-mesenchymal transition) of glioma cells." (PMID 35935338, 2022). "For further studies we have selected WG4 glioma cells due to the highest ANXA2R and FOXM1 expression in those cells." (PMID 34131149, 2021).
glioma (continued). "Since NOX4 is thought to be a source of intracellular ROS in several types of cancer and FOXM1 is aberrantly expressed in glioma, we next sought to determine the relationship between NOX4 and FOXM1." (PMID 34740322, 2021). "The expression of FOXM1 and NADPH oxidase 4 (NOX4) in normal brain tissues and glioma was detected in data from the TCGA database and in our specimens." (PMID 34740322, 2021). "As such, the interaction between FOXM1 and VEGF is key in driving angiogenesis in glioma cells, which is an important factor in tumorigenesis." (PMID 34948433, 2021). "It seems that FoxM1 suppresses NSC differentiation and promotes self-renewal by upregulation of miRNAs, and also participates in glioma, such that its effects on specific neurological and oncological conditions merit further investigation." (PMID 33691791, 2021). "The expression of FOXM1 and ANXA2R RNA-seq profiles showed a strong correlation between our samples and in 299 independent TCGA glioma samples." (PMID 34131149, 2021). "Analysis of TCGA datasets in glioma patients confirmed significant positive correlation of ITGA6 expression with CDK1, CDK4, PCNA, and FOXM1 transcript levels." (PMID 34205341, 2021). "FOXM1 binds to the promoter of VEGF, the primary growth factor involved in angiogenesis that is frequently overexpressed in glioma cell lines." (PMID 34948433, 2021). "In glioma, PHGDH identified as directly upstream of FOXM1 prevents FOXM1, a proverbial oncogene, from proteasome degradation due to ubiquitination by interacting with its N-terminal, which facilitates tumor proliferation, invasion, and tumorigenicity." (PMID 32226297, 2020). "FoxM1 overexpression significantly increased the expression of ASPM and promoted the proliferation and migration of glioma cells, which was abolished by ASPM ablation." (PMID 32667745, 2020). "Curiously, FOXM1 and E2F4 were enriched only in glioma tumors, which deserves further exploration in the next section." (PMID 32807122, 2020). "It has been reported that FoxM1 is overexpressed in GBM and suggests poor prognosis in glioma patients." (PMID 32667745, 2020). "Our results demonstrated for the first time that FoxM1 can directly activate the expression of ASPM by binding to the promoter, thereby regulating the proliferation, migration and invasion of glioma cells." (PMID 32667745, 2020). "In glioma, PHGDH interacts with and stabilizes the oncogenic transcription factor FOXM1 to promote the proliferation, invasion and tumorigenicity of glioma cells." (PMID 30744688, 2019). "Compared with those in para-tumor brain tissues, both FOXM1 and Survivin mRNA levels were up-regulated in gliomas, with increasing levels in higher WHO grade gliomas (P < 0.05 or P < 0.01)." (PMID 31796105, 2019). "The treatment of glioma cells with cyclopamine, GANT61 or siRNA against GLI1, GLI2, or GLI3 significantly decreased the expression of GLI1, FOXM1, BMI1, SOX2, and OCT4, involving in the maintenance of the stem cell state." (PMID 30730955, 2019). "FOXM1 has also been shown to promote nuclear localization of β-catenin and induction of canonical WNT target gene transcription during glioma tumorigenesis." (PMID 30717152, 2019). "Bortezomib was found to inhibit glioma growth and improved TMZ chemotherapy efficacy, probably via down-regulating the FOXM1–Survivin axis." (PMID 31796105, 2019). "The expression of GLI1, GLI2, GLI3 and their target genes FOXM1 and BMI1 was analyzed by RT-qPCR for 20 glioma cell lines and a normal adult brain tissue." (PMID 30730955, 2019). "It has been reported that FoxM1 directly binds to β-catenin and increases β-catenin nuclear localization and transcriptional activation of WNT target genes and glioma tumorigenesis." (PMID 29423068, 2018). "In glioma stem-like cell (GSC), maternal embryonic leucine-zipper kinase (MELK) increases the activity of FOXM1 by interaction with its N-terminus and promoting its phosphorylation by Plk1." (PMID 30208972, 2018).
glioma (continued). "Corroborating our results, a very recent study reported that FOXM1 binds onto UBE2C promoter and triggers its transcription in glioma cells and, therefore, protects them from autophagic cell death." (PMID 29596365, 2018). "Subsequently, we analyzed the expression levels of FoxM1, ADAM17 and mesenchymal markers (vimentin, YKL-40) in four glioma cell lines." (PMID 29700308, 2018). "Meanwhile, the Foxm1 gene downstream of GLI1, via targeting CyclinD1 and MMP-2 and regulating TGF-β1 signaling, is critical in promoting EMT of glioma cells." (PMID 28446712, 2017). "Our study focused on determining the molecular mechanism by which FoxM1 represents a pivotal transcriptional regulator of UBE2C, whose deregulation induces autophagic death in glioma cells." (PMID 28767320, 2017). "We identified both FoxM1 and MYBL2 in high-grade glioma tissues were much higher than in normal brain tissues and low-grade glioma tissues." (PMID 28784180, 2017). "However, the role and mechanism of Akt/FoxM1 signaling in the development of glioma is unknown." (PMID 28784180, 2017). "Collectively, our findings provide clinical and molecular evidence that FoxM1 promotes glioma progression by enhancing UBE2C transcription and that the inhibition of UBE2C partially induces autophagic glioma cell death." (PMID 28767320, 2017). "The colocalization of UBE2C and FoxM1 expression was confirmed by a double immunofluorescence assay, showing that the expression levels of both UBE2C and FoxM1 were correlated with the glioma histological grade." (PMID 28767320, 2017). "We then divided the glioma patients into different groups based on the mean value (3.83) of relative MYBL2 and the mean value (5.88) of relative FoxM1 expression." (PMID 28784180, 2017). "Our analysis strongly supports that the role of MYBL2 and FoxM1 in glioma progression and illustrates that increased FoxM1 activity up-regulates MYBL2 through the Akt/FoxM1 signaling cascade." (PMID 28784180, 2017). "Conversely, in high-grade glioma U251 cells, the numbers of colonies were reduced by MYBL2 and FoxM1 knockdown." (PMID 28784180, 2017). "We performed qRT-PCR analysis and Western blotting to test FoxM1 and MYBL2 expression in high-grade glioma cell lines (U251, U87, U343 and T98G), low-grade cell line (Hs683) and 9 normal tissues." (PMID 28784180, 2017). "In low-grade glioma Hs683 cells, the numbers of colonies were significantly increased by MYBL2 and FoxM1 over-expressing vector (* p < 0.05)." (PMID 28784180, 2017). "Previously, a series of in vitro and in vivo studies indicated that FoxM1 and UBE2C displayed high expression and activity levels in many cancer types, including glioma." (PMID 28767320, 2017). "In this study, we found that Forkhead box transcription factor M1 (FoxM1) overexpression increased UBE2C expression, whereas FoxM1 suppression inhibited UBE2C expression in glioma cells." (PMID 28767320, 2017). "Down regulation of FoxM1 and MYBL2 by siRNAs induced the cell cycle arrest, apoptosis and EMT of glioma cells." (PMID 28784180, 2017). "FoxM1 was also shown to be transactivated by HSF1, which promoted the survival of glioma cells under heat shock stress." (PMID 28148279, 2017). "Using qRT-PCR, we confirmed that the expression levels of FOXM1, PLAU, CYR61, THBS1 and ADAM9 are indeed significantly down-regulated upon HMGA2 depletion in TPC1115 GICs, U87MG glioma cells and SK-N-SH neuroblastoma cells." (PMID 27259253, 2016). "First, FOXM1 expression levels are positively correlated with HMGA2 expression in GBM specimens from the TCGA dataset and glioma samples from the CGGA dataset." (PMID 27259253, 2016). "Second, FOXM1 is overrepresented in GBM patients and its expression levels are inversely correlated with glioma patients' survival period using the CGGA dataset." (PMID 27259253, 2016).
glioma (continued). "First, examination of the Rembrandt glioma database showed that FoxM1 expression in gliomas was significantly higher than that in normal brain tissues and exhibited increasing tendency with the WHO grade of gliomas (grade II, III, and IV) (p-value<0.001)." (PMID 26444992, 2015). "Using 24 grade III glioma samples and 56 GBM samples, we found that FOXM1 RNA expression in individual tumors was correlated with MELK expression (p < .001)." (PMID 23404835, 2013). "We also found the total numbers of sole activators of FOXM1, PDGFRA, OPN, CYCLIN_D, CYCLIN_E, BMI, SNAI1, JAGGED2, SFRP were increased in Glioma scenario as compared to the canonical HH pathway." (PMID 23935937, 2013). "To determine the effect of increased FoxM1 expression on Anxa1 expression, we studies two human glioma cell lines, Hs683and SW1088, that had low levels of the FoxM1 expression." (PMID 23991102, 2013). "Since FOXM1 acts as an oncogene in cancers and glioma is not an exception, those miRNAs whose target is FOXM1 are usually downregulated, leading to its overexpression and exacerbating glioma’s malignancy." (PMID 37821870, 2023). "Furthermore, inactivations of Akt/FoxM1 signaling by Akt inhibitor and siRNA-FoxM1 diminish the expression of MYBL2 in glioma cells." (PMID 35935338, 2022). "It was also reported that the aberrant activation of Wnt/β-catenin pathway, which is widespread in human cancers, including pancreatic cancer, favors the interaction between FOXM1 and USP5, thereby inducing FOXM1 protein stabilization and nuclear accumulation in glioma cells." (PMID 35241126, 2022). "In addition, FOXM1 interacts with β-catenin and promotes β-catenin/TCF4-dependent transcription in glioma cells." (PMID 34117362, 2021). "Considering that FOXM1 expression is positively correlated with NOX4 expression in glioma, it is speculated that NOX4 may be involved in the regulation of FOXM1 expression." (PMID 34740322, 2021). "However, recent studies revealed that transcription factor FoxM1 bound to the promoter of ASPM and activated the transcription of ASPM directly in glioma cells and gastric cancer cells." (PMID 34428354, 2021). "Moreover, FoxM1 can promote acquisition of MES features and PMT in glioma via activation of the EGFR–AKT–GSK3β signaling pathway." (PMID 34381734, 2021). "Altogether, these results support the hypothesis of functional interactions between FOXM1 and the ANXA2R regulatory regions in glioma pathogenesis." (PMID 34131149, 2021). "Moreover, FOXM1 and HMMR genes, which promote stemness of glioma stem cells (GSC), resistant to apoptosis induced by oxidative stress and chemotherapy and regulation of tumor metastasis, are detected co-localized with TRIP13 gene." (PMID 34066132, 2021). "Comparison of FOXM1 and ANXA2R RNA-seq profiles showed a highly significant positive correlation between their expression levels in 33 samples from our cohort and in 299 TCGA glioma samples." (PMID 34131149, 2021). "In this study, we demonstrated for the first time that FoxM1 can directly regulate ASPM transcription in glioma cells, thereby affecting their expression and thereby regulating the proliferation, migration and invasion of glioma cells." (PMID 32667745, 2020). "FOXM1 enhances tumor metastasis in lung carcinoma, breast adenocarcinoma, pancreatic carcinoma, prostate carcinoma, colorectal cancer, ovarian carcinoma, cervical and nasopharyngeal carcinoma, ESCC and glioma." (PMID 32035486, 2020). "PHGDH was also recently reported to have a non-metabolic role in glioma tumorigenesis via stabilization of the transcription factor FOXM1." (PMID 32477466, 2020). "We found the expression of gli target genes, including GLI1 and FOXM1, in all tested glioma cell lines, but not in the normal tissue." (PMID 30730955, 2019). "Additionally, our previous studies showed that FoxM1 upregulated expression of PDGF-A and STAT3 to maintain the self-renewal and tumorigenicitiy of glioma stem-like cells." (PMID 29700308, 2018).
glioma (continued). "To ascertain whether FoxM1 regulate MES transition in glioma cells in an ADAM17-dependedent manner, we first knocked down ADAM17 expression in FoxM1 overexpression cells." (PMID 29700308, 2018). "Interestingly, MELK activity together with FOXM1 has been shown to positively regulate both SOX2 and EZH2 in other tumours, such as glioma and medulloblastoma." (PMID 29437778, 2018). "Furthermore, inactivations of Akt/FoxM1 signaling by Akt inhibitor and siRNA-FoxM1 reduce the expression of MYBL2 in glioma cells." (PMID 28784180, 2017). "Results showed that whether in low or high-grade glioma, the expression of MYBL2 and FoxM1 are highly correlated (LGG: Pearson’s correlation = 0.83; HGG: Pearson’s correlation = 0.65)." (PMID 28784180, 2017). "Our findings indicate a novel role of FoxM1 in the development of glioma and initially present an autophagy-related function of UBE2C, which may be a feasible target for molecular glioma therapies." (PMID 28767320, 2017). "The present study raises the possibility that FoxM1 and MYBL2 may be potential targets for cancer therapy as both play crucial roles in glioma progression." (PMID 28784180, 2017). "And, we sought to determine whether Akt/FoxM1 signaling pathway is involved in regulating MYBL2 expression and whether these factors can predict the disease progression and prognosis of the glioma patients." (PMID 28784180, 2017). "Moreover, more studies are needed to see if the feedback loop of FoxM1 and Akt signaling pathway plays a role in MYBL2 expression in glioma." (PMID 28784180, 2017). "FoxM1 might be in turn upregulated by high-mobility group AT-hook 2 (HMGA2), a protein that was demonstrated to be highly expressed in Grade II-IV gliomas, supporting GBM cell invasive behavior." (PMID 29261132, 2017). "Moreover, previous study indicates that FOXM1 directly binds to and activates the promoter of the MMP2 gene in glioma cells." (PMID 27034162, 2016). "The R6A mutant maintained cytoplasmic as well as nuclear localization of FoxM1, whereas the R15A mutant showed a significant reduction in nuclear localization of FoxM1 in SW1783 cells, suggesting that R15 is important for FoxM1 transcriptional activation and nuclear localization in glioma cells." (PMID 41323781, 2025). "In glioma cell lines (i.e., U87-MG, U251, ln18, and U373), UBE2C, a known glioma tumor progression protein, harbors two FOXM1 binding sites on its promoter, strongly suggesting that it could be another direct transcriptional target of FOXM1." (PMID 39594778, 2024). "Some studies have mentioned the positive impact of FOXM1 on the expression of growth factors, including vascular endothelial growth factor (VEGF) and epidermal growth factor receptor(EGFR) in high-grade gliomas, all necessary for the growth and proliferation of GSCs." (PMID 37821870, 2023). "Interestingly, we found that AMPK scores were significantly negatively correlated with TF expression levels in glioma: E2F4 (rho = − 0.48, P < 0.0001), EZH2 (rho = − 0.57, P < 0.0001), FOXM1 (rho = − 0.49, P < 0.0001), SMAD4 (rho = − 0.18, P < 0.0001) and SUZ12 (rho = − 0.23, P < 0.0001)." (PMID 32807122, 2020). "However, whether FoxM1 can directly regulate ASPM expression and whether the FoxM1‐ASPM axis contributes to the pathogenesis and progression of gliomas remain largely unclear." (PMID 32667745, 2020). "Additionally, TFs FOXM1 and E2F4 were identified to be enriched only in glioma tumors." (PMID 32807122, 2020). "Thus, we examined the effects of FoxM1 on ADAM17 mRNA and protein expression in glioma cells." (PMID 29700308, 2018). "FoxM1B was the predominant FoxM1 isoform in human gliomas but not in normal brain tissue." (PMID 23991102, 2013). "This interaction stabilized FOXM1 protein levels and sequentially induced the expression of a series of oncogenes, such as MMP-2, VEGF, Chk2 and cyclin D1, which suggests that in addition to metabolic functions, PHGDH may have other biological roles in glioma tumorigenesis." (PMID 23229761, 2013).